RNU6-472P (RNA, U6 small nuclear 472, pseudogene)
Gene: Small nuclear RNA gene on chromosome 12 (33,923,374 to 33,923,480, reverse strand). Ensembl gene ENSG00000207026.
Homologues: Orthologues: chimpanzee U6 (100% identical), macaque U6 (92% identical), rat U6 (85% identical), rabbit U6 (79% identical), pig U6 (79% identical), rabbit U6 (73% identical), dog U6 (72% identical), dog U6 (69% identical). Paralogues in human: RNU6-480P (88% identical), RNU6-16P (86% identical), RNU6-1099P (85% identical), RNU6-1251P (85% identical), RNU6-140P (85% identical), RNU6-144P (85% identical), RNU6-21P (85% identical), RNU6-235P (85% identical), RNU6-33P (85% identical), RNU6-46P (85% identical), RNU6-1 (84% identical), RNU6-1082P (84% identical), and 1282 more.